CD74 (CD74 molecule)
Diseases named in the same sentence as CD74 in open-access papers (continued):
Sharing a sentence is not in itself a finding about the gene and the disease.
cancer (continued). "Our results support the concept that CSCs, through the expression of MIF and CD74, become protected by energy-default processes which force cancer cells with defective mitochondria to generate energy through an AMPK-regulated glycolysis in the cytoplasm." (PMID 28114961, 2017). "In several tumoral cells (breast, colon, prostate, lung...), MIF signaling in cancer is well described to be triggered by its receptor CD74." (PMID 26883190, 2016). "The effect of MIF and CD74 on carcinogenesis seems to change with the cell type as well as the stage of the cancer." (PMID 26883190, 2016). "In this respect, our study is the first to report the semi-quantitative immunohistochemical evaluation of both expression of MIF and CD74 in serial sections of biopsy specimens, as well as their distribution between cancer cells and the peritumoral stroma." (PMID 24939415, 2014). "CD74 staining was heterogeneous and significantly decreased in cancer cells but increased in the surrounding stroma, namely in lymphocytes, macrophages and vessel endothelium." (PMID 24939415, 2014). "In the light of well documented CD74-mediated pro-survival effects, we aimed to examine the effect of CD74 on Fas-mediated apoptosis, which is required for effective killing of cancer cells by most chemotherapies and radiation." (PMID 25304249, 2014). "We anticipate that specific targeting of the CD74 on the cell surface will sensitize CD74-expressing cancer cells to Fas-mediated apoptosis, and thus will increase effectiveness of chemotherapy regimens for hematological malignancies." (PMID 25304249, 2014). "CD74-mediated proliferative and pro-survival signaling can initiate or contribute to pro-carcinogenic events and enhance the survival of cancer cells." (PMID 25304249, 2014). "These considerations led us to an immunohistochemical assessment of expression of MIF and CD74 in serial sections of human breast cancer tumor specimens, mapping their profiles in cancer and stromal cells." (PMID 24939415, 2014). "In cancer cells, immunoreactivity for CD74 signal was weak and heterogeneous, mostly located on the membrane and in the cytoplasm." (PMID 24939415, 2014). "CD74 positivity was observed in the stroma surrounding carcinomas, namely in lymphocytes (arrow), macrophages and vessel endothelium, with a similar intracellular distribution." (PMID 24939415, 2014). "Overexpression of Cd74 has been reported in some inflammatory diseases and several forms of cancer, and also known as an indicator of disease in some conditions." (PMID 23874995, 2013). "Among selected genes, CD24, CD44, and CD74 are cell surface adhesion molecules shown to be over expressed in various cancers." (PMID 19602232, 2009). "In cancer, however, CD74 expression becomes aberrantly widespread." (PMID 41597203, 2026). "On one hand, high expression of CD74 in cancer may enhance antigen presentation capacity and promote antitumor immune activation." (PMID 41597203, 2026). "Finally, a recent pan-cancer analysis involving spatial transcriptomics confirmed that CD74 is significantly upregulated in most malignancies relative to normal tissue and serves as a predictor of overall prognosis." (PMID 41597203, 2026). "Additionally, CD74 expression significantly increases in certain cancers after receiving immune checkpoint blockade (ICB) therapy, strongly indicating that CD74 activation triggers immune responses in most cancers." (PMID 40055311, 2025). "Several studies have suggested that CD74 may serve as a prognostic factor and therapeutic target for patients with malignant tumors." (PMID 40470045, 2025). "Gene Ontology (GO) and Kyoto Encyclopedia of Genes and Genomes (KEGG) analyses revealed that the top upregulated genes (start vs. end) in cancer‐pre cells (Curve1 and Curve2) were enriched in antigen processing and presentation pathways, such as CD74, HLA‐DRB1, HLA‐DRA, PSME1/2, and CTSB." (PMID 40860436, 2025).
cancer (continued). "In pan‐cancer immune research, HLA‐DR+CD74+ neutrophils have been identified as alternative antigen‐presenting cells (APCs) in diverse cancer types and can present tumour neoantigens to T cells, thereby reshaping the T‐cell immune pool and enhancing antigen‐specific responses." (PMID 39924620, 2025). "In addition to their known effects in normal cells and systems, MIF and CD74 are increasingly recognized as playing an intricate role in cancer progression." (PMID 38730725, 2024). "Given its critical cellular functions, CD74 expression also correlates with more invasive forms of cancers and was found to be a highly and differentially expressed protein in chemotherapy-resistant cells via unknown mechanisms." (PMID 39056676, 2024). "Further, both MIF and CD74 are important players in immune homeostasis and cancer." (PMID 38730725, 2024). "This showed a significant positive correlation with the contents of M1 macrophages in 32 cancers, with the exception of DLBC, suggesting that CD74 may represent a marker for infiltration by M1 macrophages in pan-cancer." (PMID 38582956, 2024). "MIF/DDT/CD74 are potential biomarkers and therapeutic targets across a variety of cancers." (PMID 38732068, 2024). "Given the poor outcome of conventional treatment in BRCA patients with low CD74 expression, we sought to identify drugs that could potentially activate CD74 and improve the sensitivity of cancer to current chemotherapy." (PMID 38582956, 2024). "The findings suggest the significance of regulated CD74 AS events in cancer progression." (PMID 38582956, 2024). "Moreover, the role of CD74 has been explored in cancer, including in the regulation of migration, invasion, and cellular signaling." (PMID 38256356, 2024). "CD74-MIF is expressed in the TME of many types of cancer after chemotherapy." (PMID 39118044, 2024). "Data on pan-cancer CD74 mRNA levels were obtained from the TCGA and GTEx databases." (PMID 38582956, 2024). "Negative associations were seen between CD74 and high-grade BRCA and UCEC, suggesting the possibility that increased CD74 levels may hinder cancer progression." (PMID 38582956, 2024). "Overexpression of CD74 was observed in 21 cancers compared with normal tissues." (PMID 38582956, 2024). "Multiple fluorescence staining showed that CD74 may represent a marker for M1 macrophage infiltration in pan-cancer." (PMID 38582956, 2024). "The results also enable us to develop cell-penetrating-peptides (CPPs) to facilitate cellular intake of AKT inhibitors associated by cargo; and/or to establish unique CD74 antibody-drug conjugate (ADC) with AKT inhibitor to target CD74-positive cancer cells selectively and efficiently." (PMID 39056676, 2024). "All these findings indicate that CD74 may be involved in the regulation of immune cell infiltration and the functions of TME-associated genes in most cancers." (PMID 38582956, 2024). "As an invariant chain, CD74 participates in several key processes of the immune system, including antigen presentation, B-cell differentiation and inflammatory signaling, in many cancer types (Borghese and Clanchy 2011a, b)." (PMID 39118044, 2024). "Interestingly, peptides from the binding domain of CD74 enhanced the sensitivity of cancer cells to FASL-induced apoptosis in MDA-MB-231 cells." (PMID 39056676, 2024). "In general, CD74 was demonstrated to play a role in the development of many types of cancers." (PMID 36945359, 2023). "To date, five in-frame CD74 fusion proteins have been reported in cancer." (PMID 37958963, 2023). "In turn, sCD74 exerts anti-survival and pro-apoptotic effects on CD74-expressing cancer cells." (PMID 36672343, 2023). "This was suggested by the authors to influence the motility and invasiveness of cancer cells and could therefore be one explanation for the correlation between high CD74 expression in triple negative tumors and their heightened metastatic propensity." (PMID 37081824, 2023).
cancer (continued). "Further studies are warranted to establish whether TIMP‐1 and CD74 function as tropism factors for cancer cells and whether targeting their interaction would result in a novel therapeutic treatment for patients." (PMID 37081824, 2023). "CD74 may have a potential role in targeted cancer therapy, using monoclonal antibodies or small molecules to block CD74 function." (PMID 35208514, 2022). "Studies on the molecular functions of CD74 in cancer cells have generally found that the MIF-CD74 signaling pathway stimulates processes that would support cancer progression such as increased cancer cell proliferation, survival and invasion." (PMID 34944801, 2021). "However, almost all pre-clinical studies on CD74 in cancer are conducted in vitro or, in a few cases, in immunodeficient mouse models." (PMID 34944801, 2021). "This could be speculated to reflect one of two scenarios: CD74 and its antigen presentation-related functions requires the presence of an immune infiltrate to have an anti-cancer effect." (PMID 34944801, 2021). "Increased CD74 expression is observed in injury, inflammation, and cancer." (PMID 32655566, 2020). "An anti-MIF mAb that has been studied in Phase II PoC in cancer patients as well as anti-CD74 mAb that is in clinical phase and would allow simultaneous blockade of MIF and DDT signaling are of even more relevant for more rapid application in the clinical setting." (PMID 31581595, 2019). "CD74 was previously shown to be decreased in cancer samples based on mRNA levels (NAP/NC ratio log2 − 0.169, CC NM/NC − 1.966 and CC M/NC − 2.601) and CEACAM-7 (NAP/NC ratio log2 − 2.054, CC NM/NC − 3.259 and CC M/NC − 3.911) based on immunohistochemistry staining." (PMID 31889941, 2019). "Furthermore, CD74 expression by stressed kidney cells raises questions about the kidney safety of cancer therapy strategies delivering lethal immunoconjugates to CD74-expressing cells." (PMID 26441987, 2015). "Unregulated cell proliferation remains a hallmark of cancer, and given the known stimulation of several central pro-proliferation pathways MIF induces upon binding to CD74, further investigation into the role of MIF in inflammation-associated cancers is warranted." (PMID 24887129, 2014). "The CD74-MIF pair could promote cancer cell growth and metastasis." (PMID 40831537, 2025). "Moreover, CD74 is upregulated and correlated with cancer cell survival and growth." (PMID 39056676, 2024). "Thus, CD74 may be important in the survival and outcome prediction in patients with cancer, suggesting its promise as a potential biomarker." (PMID 38582956, 2024). "However, whether there is a difference in the ability of high CD74 expression in cancer cells and immune cells to predict patient outcome remains unclear." (PMID 39118044, 2024). "Further analysis of the associations between CD74 and 14 functional cancer states using pan-cancer data from CancerSEA, with a specific focus on BRCA, indicated a positive association with both angiogenesis and inflammation, suggesting the involvement of CD74 in these pathways in BRCA." (PMID 38582956, 2024). "However, the function of CD74 in cancer remains poorly understood." (PMID 38582956, 2024). "Compounds that could activate CD74 in certain cancers were also investigated." (PMID 38582956, 2024). "Notably, the expression of the type II transmembrane protein, CD74, is correlated with chemotherapy-resistant and more invasive forms of cancers via unknown mechanisms." (PMID 39056676, 2024). "While the CD74 protein alone is an attractive molecular target in multiple cancers, the study of cancer-specific proteins, such as the ones described here, offer a great opportunity for refining currently utilized cancer treatment plans and developing new methods for early detection." (PMID 37958963, 2023). "Hence, a blockade of CD74 in both cancer cells and stromal cells appears to be beneficial." (PMID 36672343, 2023).
cancer (continued). "In addition, fusions of the NRG1 gene with various partner genes, such as the CD74 molecule, solute carrier family 3 member 2, and unc-5 netrin receptor D, have been identified in a wide range of cancer types, although their frequency is low with only 82 such examples out of 44,570 tumors (0.2%)." (PMID 34068503, 2021). "Subsequently, we focused on a group of six candidate genes (Cd74, Lpl, Ifi44, Sat1, Fzd9 and Wwc1) that have been reported to be frequently regulated by epigenetic mechanisms and participate in the regulation of important signal pathways during cancer development and progression." (PMID 34836197, 2021). "Therefore it is relevant to quantify the association of CD74 and CD44 in cancer cells." (PMID 29190904, 2017). "However, further studies are required to confirm the roles of CD4 and CD74 in cancers." (PMID 27323782, 2016). "In addition, as a cell membrane protein, CD74 may serve as a new target for anti-cancer therapy of HNSCC." (PMID 19602232, 2009). "Compared to controls, dual inhibition of AEP and CD74 effectively reduced EMT markers and the migratory capacity of cancer cells in vitro." (PMID 40411322, 2025). "To support their possible roles in crucial oncogenic mechanisms, we assessed the mutation frequency, copy number amplification, and copy number–expression correlation of STC2, MIF, CD74, CXCR4, GDF15, and TGFBR2 across several cancer types." (PMID 41502509, 2025). "The results demonstrated that cancer cells interact with stromal cells via the PTN-NCL and MIF-(CD74+CXCR4) signaling pathways." (PMID 40642071, 2025). "S7) there were many known and candidate “cancer genes” (again, of the Cancer Gene Census from COSMIC), including enhanced expression of NRAS, KMT2D, and CD74." (PMID 41187221, 2025). "The interaction of MIF with its receptors (CD44, CD74, CXCR4) are known drivers in late stage MM and other cancers and are involved in a variety of mechanisms, including homing to BM, pro-tumoral M0 macrophage differentiation and resistance to therapy." (PMID 41056512, 2025). "Differential gene expression and gene ranking analyses revealed that the expression of CD74, HLA-DRA, HLA-DRB1, and FXYD3 was elevated in MHC-II+ cancer cells, whereas the expression of LOXL2 and DLL4 was increased in MHC-II− cancer cells." (PMID 41281745, 2025). "Key hub genes including CD68 in BRCA, CD74 in CRC and OVCA, and TIMP1 in LUSC, played critical roles in immune-cancer cell interactions and tumorigenesis inhibition." (PMID 41370198, 2025). "Like TNBC, MIF signaling between cancer luminal A cells and CD4+ or CD8+ T cells via CD74 complexes was elevated in the older cohort." (PMID 39483921, 2024). "Detection of differential markers subtyped the cells of mesenchymal origin (vimentin, desmin, cadherin-11, podoplanin, CD74, S100A4, CD44, FAP), which vary according to the functional differentiation and specialization in sites of cancer tissue." (PMID 39575252, 2024). "As there is an overall paucity of information on the role of CD74 in cancer and no pan-cancer analysis, we conducted an extensive analysis of the gene using various publicly available databases to determine its expression levels, genomic alterations, and prognostic associations in pan-cancer." (PMID 38582956, 2024). "In our study, CD74 expression was found to be increased following cytokine treatment in several cancers, as well as following ICI treatment (anti-PD1, anti-PDL1, and anti-CTLA4), strongly suggesting that CD74 activates the immune response in most cancers." (PMID 38582956, 2024). "A strong interaction between cancer stem cells (CSCs) with high expression of ACACA and macrophages through CD74 molecule (CD74) and integrin subunit beta 1 (ITGB1) signaling was identified." (PMID 38584256, 2024). "Our results reveal hybrid cell upregulation of immune molecules, including CD74, B2M and TNFAIP3, which are known to contribute to cancer cell immune evasion." (PMID 38106024, 2023).
cancer (continued). "Genes in response to interferon gamma, including CCL20, CCL25 and CD74, and antigen presentation-related genes, such as HLA-DPA1, HLA-DRA and HLA-DRB, were significantly upregulated in the cancer cells of immune-rich type tumors." (PMID 36729271, 2023). "MIF is commonly overexpressed in many cancers and, when inhibited, anti-human MIF immunoglobulins coreceptors CD74 and CD44 are also downregulated leading to a decrease in cancer cell proliferation and migration." (PMID 37514190, 2023). "Because the mentioned three L-R pairs (CD74-COPA, CD74-APP and HLA-C-FAM3C) were observed extensively in the interactions from TAMs to cancer cells, it can be suggested that CD74 and HLA-C are highly active in TAMs." (PMID 37945567, 2023). "MIF can bind to its receptor CD74 in the TME, which is present on TAMs, DCs, Treg cells, and MDSCs, facilitating immunological escape and cancer growth." (PMID 35967424, 2022). "Assessment of genes most upregulated within NHS–rmIL-12–treated carcinoma revealed increased expression of IFN-γ–responsive genes involved in antigen presentation, including B2m, H2-A, Cd74, the immune checkpoint Cd274, and the T lymphocyte chemokine Cxcl9." (PMID 35260537, 2022). "Combining NPG with HO-1 inhibitor demonstrated down-regulation of genes involved in cancer cell invasion and proliferation (EGR1, CXCL2, AREG, CXCL3, EREG, CD3e, CD3g, CD74, and B2M) as compared to NPG or to control animals." (PMID 34066839, 2021). "The surface expression of MIF coreceptor CD74 and CD44, which promote downstream signaling pathways for cancer cell proliferation and migration, were decreased in rSmeg-hMIF-hIL-7 compared with all other groups." (PMID 34389619, 2021). "Three candidate genes (ALOX5AP, CD74, and FCGR2A) were found, all of which were expressed at higher levels in lungs and lymph nodes than in matched cancer tissues and were probably expressed in the microenvironment." (PMID 31992246, 2020). "We analyzed the cancer genome atlas (TCGA) GBMLGG database for survival and MIF expression and CD74 expression and the combination." (PMID 32625208, 2020). "Twelve genes were frequently targeted in both cohorts independently, including BCL2, BCL6, BCL7A, CD74 and CIITA, all listed as oncogenes in the Cancer Gene Census and known to be involved in lymphomagenesis." (PMID 25903198, 2015). "CD74, HLA-DR, and TAP2 were expressed at significantly higher levels in the epithelium of cancer cells derived from tumors of patients with low- versus high-volume ascites (P = 0.046, P = 0.006, and P = 0.002, resp)." (PMID 24982872, 2014). "In other cases, CD74 expression was shared between stromal and malignant epithelial cells, hinting at MIF’s involvement in autocrine regulation of angiogenic factors or inhibition of apoptosis in cancer cells." (PMID 41159021, 2025). "Applied to LUAD and LUSC datasets, our approach successfully identified a stable core set of pathogenic genes, including both highly expressed genes (e.g., CD74, HGF) and stably expressed genes (e.g., BRAF, KDM6A), which play critical roles in cancer progression." (PMID 40136480, 2025). "Extensive experimental and computational research has unveiled intricate signaling mechanisms in MIF/DDT/CD74 pathways across diverse cancer types, shedding light on the complexity of canonical and non-canonical signaling processes within the TME." (PMID 38732068, 2024). "In addition, it has been reported that CD74 is expressed mainly by the malignant cells of NSCLC and other cancers." (PMID 39001552, 2024). "Furthermore, relationships between CD74 methylation and survival prediction (OS, DSS, DFS, and PFS) were examined by KM curves for all 33 cancer types, showing that reduced methylation was predictive of longer survival in ACC and BLCA." (PMID 38582956, 2024). "Thus, CD74 in combination with MIF serves a key regulatory role in the interactions among HPC-like cells, cancer cells and innate immune cells." (PMID 39118044, 2024).